MPO (myeloperoxidase)
Diseases named in the same sentence as MPO in open-access papers (continued):
Sharing a sentence is not in itself a finding about the gene and the disease.
atherosclerosis (continued). "Quercetin prevents endothelial dysfunction by competitively inhibiting myeloperoxidase-dependent HOCl generation and NADPH oxidase-dependent O2·– production that play a crucial role in atherosclerosis." (PMID 34539312, 2021). "According to the results of current pharmacological studies, MPO and PAD4 inhibitors are effective at least for myocardial infarction, atherosclerosis, and certain autoimmune diseases, whose deterioration can lead to heart failure." (PMID 33680285, 2021). "In this study, MPO variably and positively correlated with CRP, IMT and PWV supporting its role in RA-related inflammation and atherosclerosis." (PMID 34680168, 2021). "Our previous study demonstrated extensive atherosclerosis with fibrosis and luminal narrowing in the CKD mice compared with controls after 12 and 24 weeks on an HFD and increased macrophage-derived MPO activity." (PMID 33234591, 2021). "The significant correlation between MPO products (3-chlorotyrosine and 3-nitrotyrosine) and lesion area confirms a direct relationship between MPO activity and degree of CKD atherosclerosis." (PMID 33234591, 2021). "Recently, the discovery of a novel urea-independent and MPO-mediated mechanism for carbamylation has provided a vital insight into this PTM, linking it to smoking, inflammation, and atherosclerosis." (PMID 31443320, 2019). "Enzymes, such as MPO, iNOS and NADPH oxidases, have been confirmed to participate in LDL oxidation in human atherosclerosis lesions." (PMID 29896109, 2018). "However, MPO can be found in some macrophage subpopulations including resident tissue macrophages such as Kupffer cells, peritoneal macrophages, and microglia, as well as in organ infiltrating macrophages in various inflammatory diseases including atherosclerosis, multiple sclerosis (MS), and AAV." (PMID 26904693, 2016). "Because inflammation contributes to atherosclerosis generation, inflammatory biomarkers such as CRP and MPO are usually used to diagnose and assess the prognosis of coronary artery disease." (PMID 26405438, 2015). "Myeloperoxidase (MPO) is a peroxidase enzyme stored in neutrophils and a key mediator of inflammatory and redox-dependent processes in atherosclerosis." (PMID 25993296, 2015). "The complex process of atherosclerosis begins when LDL molecules are deposited in thearterial walls and undergo oxidation by reactive oxygen species (ROS) or enzymessuch as myeloperoxidase or lipoxygenase." (PMID 26196108, 2015). "It should be noted that myeloperoxidase is an early marker of vascular dysfunction and plays a crucial role in oxidative modification of LDL and hence in pathogenesis of atherosclerosis." (PMID 23637826, 2013). "We recently synthesized a novel small molecule inhibitor of MPO, INV-315, and investigated its pharmacokinetics, safety and efficacy in a model of atherosclerosis." (PMID 23251382, 2012). "HDL, isolated from atherosclerotic lesions, contains a large number of MPO-modified peptides, such as chlorinated, nitrated, and sulfoxidated apoA-I, demonstrating the correlation between the modifying effect of MPO on HDL and the development of atherosclerosis." (PMID 38275657, 2024). "Myeloperoxidase oxidized LDL (Mox-LDL) is considered to be the most patho-physiologically relevant type of modified LDL and has been reported to be ubiquitously present in atheroma plaques of patients with atherosclerosis." (PMID 39201490, 2024). "Among these, myeloperoxidase (MPO), a heme-containing and highly oxidative enzyme released by neutrophils and inflammatory monocytes, macrophages, and microglia, is a key marker of inflammation and is involved in atherosclerosis and post-MI pathophysiology." (PMID 36982778, 2023). "Both MPO and CYCS are key targets with the highest degree values, and there are numerous studies demonstrating the involvement of MPO in the development and progression of atherosclerosis." (PMID 37405052, 2023).
atherosclerosis (continued). "In addition, a significant reduction in subclinical markers of atherosclerosis, such as small and dense LDL particles, myeloperoxidase (MPO), sP-selectin, and leukocyte adhesion, was reported." (PMID 37047352, 2023). "Recently, we showed that MPO-DNA complexes measured in healthy subjects without symptomatic atherosclerosis were generally very low." (PMID 35679310, 2022). "There are only a few articles that tend to demonstrate a possible protective effect of Mox-LDLs and MPO on the clinical manifestations of atherosclerosis, and none of the studies have been conducted in humans." (PMID 35624738, 2022). "Because of their effects on the antioxidant enzyme system, including lipoxygenases (LOXs), myeloperoxidase (MPO), nicotinamide adenine dinucleotide phosphate (NAD[P]H) oxidase, catalase, GPX, and superoxide dismutase (SOD), statins can reduce atherosclerosis by their antioxidant effects." (PMID 35268403, 2022). "MPO expression and oxidation products colocalized with macrophages suggesting a crucial role for macrophage MPO in the artery wall in the pathogenesis of CKD atherosclerosis." (PMID 33234591, 2021). "In contrast, in a study by Golubinskaya and colleagues, MPO knockout mice with intact renal function and without atherosclerosis or blood pressure changes had similar vascular responses to acetylcholine as the controls." (PMID 33234591, 2021). "With a particular focus on atherosclerosis imaging, we highlight recent approaches to report on the activity of cathepsins (K and B), matrix metalloproteinases (MMP-2 and MMP-9), thrombin, heme oxygenase-1 (HO-1) and myeloperoxidase (MPO)." (PMID 34605500, 2021). "A recent study found that MPO-derived products, such as protein-bound oxidized tyrosine moieties 3-chlorotyrosine, 3-nitrotyrosine, and o,o′-dityrosine, are very important for in chronic kidney disease (CKD)-accelerated atherosclerosis." (PMID 32629758, 2020). "A transient increase in MPO, consequent to a single HFM, is not likely to be harmful to an otherwise healthy individual free of underlying atherosclerosis." (PMID 29572498, 2018). "Myeloperoxidase (MPO) is a heme-containing peroxidase expressed in neutrophils and monocytes, and it is believed to produce ROS that contribute to lipid oxidation in atherosclerosis." (PMID 28862654, 2017). "The anti-inflammatory and antioxidant effects of HDL may be promoted by decreasing serum MPO activity and increasing PON1 activity, thus deterring the development of atherosclerosis." (PMID 25604880, 2015). "Since MPO-oxidized apolipoprotein A-I (apoA-I) impairs the cellular cholesterol efflux by ABCA1, INV-315 may retard atherosclerosis development via inhibition of HDL oxidation." (PMID 23251382, 2012). "Myeloperoxidase (MPO) is a hemoprotein produced by polymorphonuclear neutrophils and macrophages and is thought to play a role in atherosclerosis through its role in inflammation and oxidative modification of low-density lipoprotein (LDL) and high-density lipoprotein (HDL)." (PMID 23251382, 2012). "Basil extract can be used as an MPO inhibitor and as a nondrug treatment for atherosclerosis." (PMID 40421013, 2025). "Thus, considering that the control group here included patients with different vascular diseases, including those resulting from atherosclerosis, the high plasma MPO levels were not surprising." (PMID 39766232, 2024).
atherosclerosis (continued). "Similarly, an unexpected protective role for MPO was found in murine atherosclerosis, where in the absence of MPO larger aortic legions and inflammation was observed." (PMID 33959129, 2021). "Moreover, a number of epidemiological and clinical studies have shown that neutrophil-associated proteins in plasma, such as matrix metalloproteinase (MMP)-9 and myeloperoxidase (MPO), predict cardiovascular outcome and also relate to the extent and severity of atherosclerosis." (PMID 30726210, 2019). "Therefore, the vascular dysfunction observed in CKD mice might be independent of atherosclerosis extent and bone marrow MPO and likely involves other CKD-specific factors that require further exploration in future studies." (PMID 33234591, 2021). "Together, the noncatalytic functions entail MPO and PON in modulating the involvement of monocytes and endothelial cells in atherosclerosis." (PMID 41704870, 2026). "Thus, we proposed that MPO and PON1 may be involved in atherosclerosis by acting as proteins, rather than enzyme activities." (PMID 41704870, 2026). "Studies performed by the same group showed that increased MPO originating from damaged macrophages colocalized with 3-NT and o,o’-tyrosine residues in atherosclerotic plaques in five-sixth-nephrectomized mice, a mouse model of CKD atherosclerosis; unlike non-CKD mouse models of atherosclerosis." (PMID 40002748, 2025). "Therefore, both MPO and alternate non-MPO pathways may play a role in non-CKD atherosclerosis." (PMID 33234591, 2021).
microscopic polyangiitis (160 papers, 2001 to 2026). Microscopic polyangiitis (MPA) is an inflammatory, necrotizing, systemic vasculitis that affects predominantly small vessels (i.e. small arteries, arterioles, capillaries, venules) in multiple organs. "The presence of PR3-ANCA is highly suggestive (80%) of granulomatosis with polyangiitis (GPA), while MPO-ANCA is associated (70%) with microscopic polyangiitis (MPA)." (PMID 38139045, 2023). "Microscopic polyangiitis (MPA) is an anti-neutrophil cytoplasmic antibody (ANCA)-associated small-vessel vasculitis typically with myeloperoxidase (MPO)-ANCA in serum." (PMID 36527167, 2022). "Sera from patients with MPO-ANCA-associated microscopic polyangiitis were found to have a high ability to induce NET formation." (PMID 36421487, 2022). "In contrast, in patients with MPO-ANCA-associated microscopic polyangiitis (MPA) DNase activity was shown to be reduced." (PMID 35619694, 2022). "The second confirmatory study of the presence of anti-DNase antibodies that interfere with NET degradation was described in subjects affected by MPO-ANCA-associated microscopic polyangiitis (MPA)." (PMID 34685647, 2021). "Serum 20S-proteasome was measured by ELISA in 44 patients with MPO-ANCA-associated microscopic polyangiitis (MPA) and renal involvement." (PMID 32864569, 2020). "We analyzed the cases of 44 patients with MPO-ANCA-associated microscopic polyangiitis (MPA) and renal involvement." (PMID 32864569, 2020). "We present a case of thymoma-associated microscopic polyangiitis with positivity for three ANCAs: MPO-ANCA, PR3-ANCA and azurocidin-ANCA." (PMID 30961527, 2019). "Myeloperoxidase (MPO)-positive perinuclear antineutrophil cytoplasmic antibodies (P-ANCA) are most commonly associated with microscopic polyangiitis, but they can also be found in granulomatosis with polyangiitis and eosinophilic granulomatosis with polyangiitis." (PMID 40777707, 2025). "PR3‐ANCA (C‐ANCA) is associated mainly with GPA, and MPO‐ANCA (P‐ANCA) is associated with microscopic polyangiitis (MPA); however, as seen in our case, discordant ANCA types, such as P‐ANCA‐positive GPA, are sometimes observed in certain populations, particularly in Asia." (PMID 41210409, 2025). "Finally, MPO-specific markers are strongly associated with microscopic polyangiitis and other autoimmune diseases." (PMID 38659590, 2024). "Microscopic polyangiitis (MPA) is predominantly characterized by rapidly progressive glomerulonephritis (RPGN) associated with myeloperoxidase anti-neutrophil cytoplasmic antibodies (MPO-ANCA)." (PMID 38873394, 2024). "Furthermore, sera from patients with MPO-ANCA-associated microscopic polyangiitis or systemic lupus erythematosus show impaired capacity for NET degradation, partly due to lower serum DNase1 levels." (PMID 36421487, 2022). "The link between NET formation and ANCA-associated vasculitis has also been examined by analyzing how immune complexes with IgG can induce NETosis by activating neutrophils through the crosslinking of the Fcγ receptor IIIb 131 in patients with MPO-ANCA-associated microscopic polyangiitis 27,28." (PMID 33746569, 2021). "Microscopic polyangiitis (MPA) is a pauci-immune necrotizing small-vessel vasculitis strongly associated with myeloperoxidase antineutrophil cytoplasmic antibody (MPO-ANCA)." (PMID 41179045, 2025). "Microscopic polyangiitis (MPA) is a pauci-immune small-vessel vasculitis associated with anti-neutrophil cytoplasmic antibodies (ANCAs), primarily targeting myeloperoxidase (MPO)." (PMID 40688963, 2025). "Microscopic polyangiitis (MPA) is associated with myeloperoxidase‐antibody positivity and pulmonary complications." (PMID 40641494, 2025). "Myeloperoxidase anti-neutrophil cytoplasmic antibody (MPO-ANCA)-associated microscopic polyangiitis (MPA) is a rare but life-threatening small vessel vasculitis in childhood." (PMID 39280366, 2024).
microscopic polyangiitis (continued). "Granulomatosis with polyangiitis (GPA) and microscopic polyangiitis (MPA) are autoimmune vasculitides associated with antineutrophil cytoplasm antibodies that target proteinase 3 (PR3) or myeloperoxidase (MPO) found within neutrophils and monocytes." (PMID 36801813, 2023). "C-ANCA targeting proteinase-3 (PR3) has been associated with granulomatosis with polyangiitis (GPA), whereas P-ANCA targeting MPO is associated with microscopic polyangiitis (MPA)." (PMID 34440897, 2021). "Investigations confirmed myeloperoxidase (MPO)-ANCA-positive microscopic polyangiitis with co-existent definitive antiphospholipid syndrome and atypical "immune-complex-mediated" renal deposits." (PMID 42037919, 2026). "The translation of TNF-α blockade (i.e., infliximab and etanercept) into a therapy for ANCA-associated GN (ANCA GN), including patients with granulomatosis with polyangiitis (GPA) (PR3-ANCA) and microscopic polyangiitis (MPO-ANCA), has faced challenges." (PMID 40735321, 2025). "Primary vasculitides are associated with cytoplasmic staining targeting PR3 (cANCA), typical for granulomatosis with polyangiitis (GPA), and perinuclear staining targeting MPO (pANCA), typical for microscopic polyangiitis (MPA)." (PMID 41008681, 2025). "Background and Objectives: To investigate whether myeloperoxidase (MPO)-antineutrophil cytoplasmic antibody (ANCA) titres at diagnosis are associated with the risk of end-stage kidney disease (ESKD) progression in patients with microscopic polyangiitis (MPA) treated with rituximab." (PMID 41303729, 2025). "ANCA serves as a specific serological marker for ANCA-associated vasculitis, with target antigens MPO and PR3 playing a major role in the diagnosis of microscopic polyangiitis and granulomatosis with polyangiitis, respectively." (PMID 40453087, 2025). "Most of these patients were MPO-ANCA positive with microscopic polyangiitis features, while others were PR3-ANCA positive with GPA features." (PMID 41300921, 2025). "Conversely, perinuclear ANCA (p-ANCA) with anti-MPO specificity typically orientates towards microscopic polyangiitis (MPA) or eosinophilic granulomatosis with polyangiitis (EGPA)." (PMID 39001306, 2024). "Myeloperoxidase antineutrophil cytoplasmic antibody (MPO-ANCA) microscopic polyangiitis is a rare but life-threatening small vessel vasculitis in childhood that affects multiple systems." (PMID 39280366, 2024). "High-resolution computed tomography (HRCT) often reveals interstitial lung changes in AAV patients, particularly in those with microscopic polyangiitis and MPO-ANCA positivity." (PMID 39001306, 2024). "In patients with anti-MPO-ANCA-associated microscopic polyangiitis, the induction of NETs correlated with ANCA affinity for myeloperoxidase and disease activity." (PMID 38001978, 2023). "Anti-proteinase 3 activity (PR3-ANCA) is most common in GPA, while patients with microscopic polyangiitis and Churg–Strauss syndrome are most often anti-myeloperoxidase ANCA (MPO-ANCA) positive." (PMID 35897050, 2022). "Serum MPO has been shown to be elevated in ANCA-associated vasculitis, including microscopic polyangiitis and eosinophilic granulomatous polyangiitis, while sputum MPO has been shown to correlate positively with sputum YKL-40 levels and sputum neutrophils." (PMID 35626330, 2022). "The majority of patients with the clinical syndrome of granulomatosis with polyangiitis (GPA) have ANCA to proteinase 3 (PR3), whereas most patients with microscopic polyangiitis (MPA) have ANCA directed against myeloperoxidase (MPO)." (PMID 36125911, 2022). "Antineutrophil cytoplasmic antibody (ANCA) is well known to be pathogenic and to have diagnostic value for ANCA-associated vasculitis, and thus, myeloperoxidase-ANCA (MPO-ANCA) has been thought to be related to the pathogenesis of microscopic polyangiitis (MPA)." (PMID 34732182, 2021). "Subsequently, he tested positive for p-ANCA and anti-MPO antibodies consistent with microscopic polyangiitis." (PMID 34235045, 2021).